KDR (kinase insert domain receptor)
Diseases named in the same sentence as KDR in open-access papers (continued):
Sharing a sentence is not in itself a finding about the gene and the disease.
renal carcinoma (41 papers, 2010 to 2026). A carcinoma arising from the epithelium of the renal parenchyma or the renal pelvis. "Next, we tested for associations between expression and methylation of FLT1 and KDR in renal cancer tissues." (PMID 26380584, 2015). "Other gene mutations, such as FANCD2, FAT3, KDM6A, KDR, TET2, and TSC2, occurred twice in this MA cohort, which was quite different from other common types of renal carcinoma." (PMID 30111351, 2018). "In the present study, we aimed to analyze whether epigenetic alterations in FLT1 and/or KDR are related to the anti-cancer effects of drugs targeting VEGF-VEGFR signaling in renal cancer cells (RCCs) and in tissues collected from renal cancer patients." (PMID 26380584, 2015). "Here, we evaluated the effects of FLT1 and KDR promoter hypermethylation combined with drugs targeting VEGF-VEGFR signaling on cancer-related phenotypes in renal cancer cells (RCCs) and examined changes in FLT1 and KDR promoter hypermethylation in tissues from patients with renal cancer." (PMID 26380584, 2015). "To evaluate whether the methylation statuses of VEGF, FLT1, or KDR of renal cancer tissues are related to patient responses to sunitinib, we compared the methylation statuses of these targets in cancer tissues from 13 patients with RCC who were treated with sunitinib." (PMID 26380584, 2015). "Among these genes specific to Cox-nnet, many have been previously reported to relevant to renal carcinoma development and prognosis, such as CASP9, TGFBR2, KDR (VEGFR)." (PMID 29634719, 2018). "This core was composed of several proteins with angiogenic functions in renal cancer including VEGFA, NRP1 and KDR (VEGF receptor-2), the latter of which may have predictive value in ccRCC." (PMID 29861861, 2018). "To evaluate whether epigenetic gene silencing occurs in renal cancer tissue, we analyzed the relationship between promoter methylation and expression of VEGF, FLT1, and KDR in normal vs. cancer tissues collected from eight renal cancer patients." (PMID 26380584, 2015).
bladder cancer (40 papers, 2006 to 2024). "As the results derived from CellphoneDB were based on the expression levels of ligands and receptors in distinct cell types, this phenomenon could be attributed to the expression levels of FLT1 and KDR in the endothelial cells of bladder cancers." (PMID 39628692, 2024). "As the results derived from CellphoneDB are based on the expression profiles of ligands and receptors 29, the expression level of FLT1 in the endothelium of bladder cancer might be higher than that of KDR." (PMID 39628692, 2024). "Expression of KDR has also been demonstrated in tumors of epithelial origin and the best rules in this study imply that the expression level of KDR is consistently lower in relation to ICAM1 and MAP2K6 when there is nodal involvement in bladder cancer." (PMID 16780590, 2006). "However, it must be kept in mind that in the present study, it is not the absolute expression of KDR that contributes to the correlation with nodal involvement in bladder cancer, but its relationship to the values of the other two genes." (PMID 16780590, 2006).
leukemia (36 papers, 2008 to 2025). A malignant (clonal) hematologic disorder, involving hematopoietic stem cells and characterized by the presence of primitive or atypical myeloid or lymphoid cells in the bone marrow and the blood. "These antibodies bound specifically the VEGF receptor 2 (VEGFR2), blocked the VEGF/KDR interaction, and inhibited VEGF-induced proliferation of human endothelial cells and migration of KDR leukemia cells." (PMID 29379493, 2017). "Our data obtained from primary endothelial cells and from leukemia/lymphoma cell lines show that KDR and FLT4 are epigenetically regulated genes." (PMID 22251800, 2012). "KDR was thought to be exclusively expressed in adult endothelial cells; however, KDR expression has been observed in multipotent hematopoietic stem cells and certain leukemias, as these cells share hemangioblasts, which are common precursors of endothelial cells." (PMID 38918393, 2024). "Real-time (RT) PCR analysis was performed to quantify KDR and FLT4 expression in some ninety leukemia/lymphoma cell lines, human umbilical vein endothelial cells (HUVECs) and dermal microvascular endothelial cells (HDMECs)." (PMID 22251800, 2012). "Additionally, studies have eluded to the fact that not only VEGF signals through receptor expression VEGFR-1 (Flt-1) and VEGFR-2 (FlK-2/KDR) specifically regulate endothelial function, but are also involved in the growth regulation of subsets of tumor cells such as leukemia." (PMID 22566481, 2012). "Expression of KDR and FLT4 was observed in cell lines from various leukemic entities, but not in lymphoma cell lines: 16% (10/62) of the leukemia cell lines expressed KDR, 42% (27/65) were FLT4 positive." (PMID 22251800, 2012).
cervical carcinoma (33 papers, 2009 to 2025). A carcinoma arising from either the exocervical squamous epithelium or the endocervical glandular epithelium. "‘Vessel maturation’ adhesion markers were correlated with KDR encoded VEGFR2 expression, which has been described before and suggests that VEGFR2 might primarily be involved in vessel maturation in cervical cancer." (PMID 25889974, 2015). "A PPIN of 90 genes identified FLT1, IGF2, IRS1, JUN, KDR, ZEB1, TIMP2 (downregulated), and EZH2, SOX2, and MYB (upregulated) in cervical cancer samples when compared with normal samples." (PMID 36879084, 2023).
Hyperglycemia (33 papers, 2011 to 2026). An increased concentration of glucose in the blood. "Placentas from women with hyperglycemia contain high levels of VEGF and VEGF receptor 2 (KDR), but reduced expression of VEGF receptor 1 (Flt-1) compared to normoglycemic women." (PMID 28817576, 2017).
myocardial infarction (33 papers, 2010 to 2025). Gross necrosis of the myocardium, as a result of interruption of the blood supply to the area, as in coronary thrombosis. "The results of our study are consistent with those of Kariz and Petrovic, who reported an association between the KDR rs2071559 polymorphism and myocardial infarction (MI) in Caucasians with T2DM in the Slovenian population." (PMID 39273385, 2024). "This is consistent with the fact that KDR/Flk-1 expression appears in macrophages and fibroblast cells found in the necrotic area after myocardial infarction." (PMID 32230747, 2020). "This research highlights key genes associated with mitochondrial oxidative stress—VCL, ABCB1, JAK2, KDR, NGF—that show differential expression in DCM and myocardial infarction." (PMID 40217309, 2025). "Some reports demonstrated that myocardial infarction was related to angiogenesis factors, including vascular endothelial growth factor-α (VEGFA), HIF-1 (hypoxia-inducible factor-1), and KDR (kinase insert domain receptor)." (PMID 31192006, 2019). "In 25 control subjects, 65 patients with coronary artery disease (CAD; 40 stable CAD, 25 acute coronary syndrome/acute myocardial infarction (ACS)), EPC were quantified using the following approach: Whole blood was incubated with CD45, KDR, and CD34." (PMID 21072182, 2010).
coronary artery disease (32 papers, 2008 to 2026). "Several studies have reported the genetic polymorphism of the KDR gene implicating the risk of coronary artery diseases." (PMID 24599305, 2014). "It has been reported that clopidogrel enhances atorvastatin-induced mobilization of EPCs as demonstrated by the presence of CD34+/CD133+/KDR + cells in patients with coronary artery disease." (PMID 33113567, 2021). "Moreover, KDR −604C, 1192A, and 1719A alleles of chromosome 4 were associated with decreased VEGF binding activity and coronary artery disease." (PMID 23077562, 2012). "Indeed, studies have reported that HDL cholesterol levels correlate with the number of circulating CD34+/KDR+ EPCs in subjects with coronary artery disease, and with the number of CD34+/CD133+ EPCs in hypercholesterolemic subjects and in obese non diabetic women." (PMID 29866130, 2018). "In our study, patients with a higher SYNTAX score, which is an indicative of higher atherosclerotic burden and more severe ischemic heart disease, had a lower number of CD34+KDR+ and CD34+CD38− cells." (PMID 28819363, 2017). "In coronary artery disease, fewer CD34+KDR+ cells are seen while in heart failure or atherosclerotic disease progression more CD34+KDR+ cells occur in circulation." (PMID 28278173, 2017). "There were 12 angiogenesis-related targets of salidroside in coronary heart disease, among which FGF1 (r = 0.237, P = 2.597E-3), KDR (r = 0.172, P = 3.007E-2) and HIF1A (r = -0.211, P = 7.437E-3) were correlated with the coronary flow index (CFI), and salidroside docked well with them." (PMID 37308900, 2023). "Furthermore, no changes in the quantity of CD34+/KDR+/CD45dim cells were observed after 12 weeks of either intermittent or continuous aerobic exercise in patients diagnosed with coronary artery disease (CAD)." (PMID 38745840, 2024).
endometriosis (32 papers, 2010 to 2025). The growth of functional endometrial tissue in anatomic sites outside the uterine body. "Here we report the discovery of a new endometriosis susceptibility locus on 4q12 (rs17773813[G], OR=1.28; P=3.8 × 10−11), upstream of KDR encoding vascular endothelial growth factor receptor 2 (VEGFR2)." (PMID 27453397, 2016). "The involvement of KDR in endometriosis risk highlights the importance of the VEGF pathway in the pathogenesis of the disease." (PMID 27453397, 2016). "One of the differentially methylated sites, cg01340163, located in the KDR gene promoter on 4q12, has an associated mQTL in endometrium where the mQTL SNP (rs12331597) is in high LD (r2 = 0.97) with an endometriosis-associated variant in this locus (rs1903068)." (PMID 37587191, 2023). "Five mSNPs associated with DNAm probe sites closest to GREB1, C11orf46, NR2C1, KDR and WNT4 are located within regions associated with endometriosis risk." (PMID 30871624, 2019). "One of the loci is upstream of KDR, implicating the VEGF pathway in the pathogenesis of endometriosis." (PMID 27453397, 2016).
hemangioma (31 papers, 2005 to 2025). A benign vascular lesion characterized by the formation of capillary-sized or cavernous vascular channels. "KDR-associated diseases are inclusive of hemangioma and capillary infantile, and its related pathways are proteoglycans in cancer and Notch-mediated HES/HEY network." (PMID 35075370, 2022).
lung adenocarcinoma (30 papers, 2014 to 2025). A carcinoma that arises from the lung and is characterized by the presence of malignant glandular epithelial cells. "KDR, also known as VEGFR-2, has been identified as a significant therapeutic target in A549 lung adenocarcinoma cells." (PMID 38260532, 2025). "For instance, KDR inhibitors have been shown to decrease the malignant potential of lung adenocarcinoma cells by downregulating EZH2 expression and increasing sensitivity to chemotherapy." (PMID 38260532, 2025). "Lung adenocarcinoma patients with WSE showed a distinctive mutated profile for the SMARCB1, ATM, EGFR exon 7, RET and KDR genes." (PMID 30093964, 2018). "KDR p.Q472H was identified in 7/10 lung adenocarcinomas and 1/1 mixed NSCLC/SCLC." (PMID 28773588, 2016). "Furthermore, three genes were among the top 20 most frequently mutated genes in lung adenocarcinoma: EGFR (34%), ATM (5%) and KDR (5%)." (PMID 24646369, 2014). "We hypothesize that carcinogens released by WSE produce frameshift truncations, resulting in loss of protein function in the tumor suppressors ATM and SMARCB1, and subsequent mutations in the oncogenes RET, KDR and EGFR exon 7 among others involved in the development of lung adenocarcinoma." (PMID 30093964, 2018). "ESR2 mRNA levels were significantly downregulated in patients with lung adenocarcinoma (LUAD) getting worse, and KDR levels were lower in lung squamous cell carcinoma (LUSC) than those in normal tissue." (PMID 34497656, 2021). "On this study we describe a landscape of genomic alterations in lung adenocarcinoma patients with WSE in the tumor suppressors SMARCB1 and ATM, in addition to the oncogenes EGFR, RET and KDR." (PMID 30093964, 2018).
Obesity (30 papers, 2009 to 2026). Accumulation of substantial excess body fat. "Consistent with our mouse data, both VEGFA and KDR gene expression exhibited a clear upward trend in obesity, while VEGFA was significantly upregulated in prediabetes/T2D, showing a strong correlation with hemoglobin A1c (HbA1c) levels." (PMID 40488531, 2025). "We also demonstrate, for the first time, elevated plasma EMP levels and unchanged circulatory CD133+/KDR+ angiogenic cells in Class III obesity." (PMID 23342053, 2013).
type 2 diabetes (29 papers, 2012 to 2025). "In observational studies of people with type 2 diabetes, the count of CD34+KDR+ cells negatively correlated with the severity of diabetic complications, meaning fewer cells were associated with more severe disease." (PMID 41009758, 2025). "The first evidence indicated that a 4-week treatment with sitagliptin increased circulating EPC number (CD34+ and KDR+ cells) in a non-randomised study conducted in a small group of patients with type 2 diabetes." (PMID 28231835, 2017).
brain tumors (27 papers, 2008 to 2025). "Targeting the VEGF pathway, including VEGF and KDR, has been explored as a potential therapeutic strategy for brain tumors." (PMID 38612588, 2024).
emphysema (27 papers, 2004 to 2026). "The CD34+KDR+CD133+ endothelial progenitor cells were associated inversely with emphysema extent." (PMID 28291826, 2017). "In contrast, CD34+KDR+ and CD34+KDR+CD133+ cells were reduced in panlobular emphysema and with reduced diffusing capacity, possibly suggesting a loss of bone-marrow-derived EPCs in that form of the disease." (PMID 28291826, 2017). "CD34+KDR+CD133+ EPCs were preferentially lower with greater emphysema on CT and both EPC populations were lower with greater panlobular emphysema and reduced diffusing capacity." (PMID 28291826, 2017). "Evaluation by emphysema subtypes demonstrated that CD34+KDR+ and particularly CD34+KDR+CD133+ EPCs were significantly decreased with increasing extent of panlobular emphysema." (PMID 28291826, 2017). "Interestingly, a different situation may occur in emphysema, where the extent of emphysema was related to less mature progenitors (CD34+KDR+CD133+) and particularly in panlobular emphysema." (PMID 28291826, 2017).
preeclampsia (27 papers, 2012 to 2025). Preeclampsia is a hypertensive disorder of pregnancy that is characterized by new-onset hypertension with proteinuria presenting after 20 weeks of gestation, and depending on mild or severe forms may initially present with severe headache, visual disturbances, and hyperreflexia. "Decreased expression of VEGFA, PGF, and KDR mRNA in placentas from pregnancies complicated by gestational hypertension was also observed, as well as reduced expression of VEGFA mRNA in placentas from pregnancies complicated by SGA with normal pressure." (PMID 38238614, 2024). "Offspring from preeclampsia exhibited diminished brain cortex angiogenesis, associated with lower circulating VEGF/PlGF/KDR protein levels, impaired brain endothelial migration, and dysfunctional assembly of F-actin filaments." (PMID 37767691, 2023). "We observed several differentially methylated CpG sites in the promoter regions of VEGF, FLT-1 and KDR between the normotensive and preeclampsia groups." (PMID 23621880, 2013). "However, because PlGF does not bind to the important VEGF signaling receptor VEGFR-2 (also known as KDR), its role in preeclampsia was debated." (PMID 39087479, 2024). "Our data indicates altered DNA methylation patterns in the VEGF, FLT-1 and KDR genes in preeclampsia as compared to the normotensive group, which could be involved in the pathophysiology of preeclampsia." (PMID 23621880, 2013). "Accordingly, reduced cell migration and proliferation were found in brain endothelial cells (mice and humans) exposed to serum/plasma from off-spring of preeclampsia; however, how these cellular outcomes might relate to the phosphorylation of the KDR warrants further investigation." (PMID 37767691, 2023). "In conclusion, our study demonstrates that offspring of preeclampsia exhibit a reduction in brain cortex angiogenesis, which is likely contributed by reduced levels of circulating VEGF/PlGF/KDR proteins." (PMID 37767691, 2023). "Likewise, the VEGF receptors VEGFR-1 (Flt-1) and VEGFR-2 (KDR/Flk-2) play roles in various vascular diseases, such as preeclampsia." (PMID 32260158, 2020). "However, mean promoter CpG methylation could not account for the higher expression of FLT-1 and KDR in preterm preeclampsia as compared to normotensive group." (PMID 23621880, 2013). "Reduced protein levels of KDR, without changes in the synthesis or release of VEGF or in the 951-tyrosine phosphorylation of KDR, were also found in hCMEC/D3 cells exposed to fetal plasma from preeclampsia." (PMID 37767691, 2023).
Cerebral ischemia (26 papers, 2012 to 2026). Restriction of arterial blood supply to the brain associated with insufficient oxygenation to support the metabolic requirements of the tissue. "Molecular docking analysis revealed lower binding energies of TB-2 with SRC, MAPK1, and KDR, and the significant role of these targets in cerebral ischemia treatment has been documented in previous literature." (PMID 39376614, 2024). "Further network pharmacology and molecular docking analyses indicate that TB-2 possesses a potential therapeutic effect against cerebral ischemia, and its possible targets were SRC, MAPK1 and KDR." (PMID 39376614, 2024). "The results of network pharmacology suggest that catalpol is involved in the regulation of inflammation, vascular homeostasis, and vascular remodeling after cerebral ischemia, which is closely related to F2, MMP9, VEGF/KDR, and ALB." (PMID 33505489, 2021). "The core intersecting targets between cerebral ischemia and TB-2 are EGFR, SRC, GSK3B, MAPK1, and KDR, which may serve as potential therapeutic targets." (PMID 39376614, 2024).
metastatic disease (26 papers, 2009 to 2025). "Recently, however, comparative mutational genomic analysis of samples taken from a patient with ENB at the time of initial presentation and following recurrent metastatic disease showed new acquired mutations in KDR, MYC, SIN3B, and NLRC4 genes with disease progression." (PMID 24672769, 2014). "However, in the original surgical resection specimen (prior to evidence of metastatic disease), mutations in KDR, MYC, SIN3B, and NLRC4 genes were not present, suggesting that these were acquired with disease progression and/or as a result of post-treatment effects." (PMID 22649506, 2012).
ischemic stroke (24 papers, 2014 to 2025). A stroke disorder caused by obstruction of blood flow to the brain, due to thrombotic (local blood clot formation) or embolic (due to a blood clot or other material traveling from another site) event. "There were different levels of CD34+KDR+ EPC-EXs at different times during ischemic stroke, which may be used as biomarkers for diseases and indicators for the prognosis of and therapeutic efficacy for ischemic stroke." (PMID 34513956, 2021).